ATM (ATM serine/threonine kinase)
Diseases named in the same sentence as ATM in open-access papers (continued):
Sharing a sentence is not in itself a finding about the gene and the disease.
cancer (continued). "The enhancement of IR-stimulated ATM activity by RSV provides a framework for upregulation of the ATM-AMPK-p21cip1 pathway in RSV-treated cancer cells and a rationale for the observed inhibition of cell cycle and survival." (PMID 22029423, 2011). "Genetic analyses indicated that early in tumourigenesis (before genomic instability and malignant conversion), human cells activate an ATR/ATM-regulated DNA damage response network that delays or prevents cancer." (PMID 21747934, 2011). "Other reported mechanisms for genistein in cancer cells include oxidative DNA damage by ROS generation in the presence of copper, and inhibition of topoisomerase II in an ATM-dependant manner." (PMID 22247744, 2011). "Blocking the ATM kinase with specific inhibitors suppresses p21 expression and induces apoptosis, suggesting that p21 acts downstream of ATM to promote cancer chemoresistance." (PMID 21637851, 2011). "Semi-quantitative immuno-blotting provided a reliable and reproducible method to compare levels of the ATM protein for a rare cohort of 20 cancer patients selected on the basis of their severe adverse normal tissue reactions to radiotherapy." (PMID 20678261, 2010). "Amongst the cDNAs expressed at a lower level in R37-OPN cells were previously characterized cancer suppressor genes PTEN, ATM and BRCA1 associated protein 1 with decreases of 19, 23 and 23 fold, respectively." (PMID 19192273, 2009). "It is also likely, that the genetic make up of a particular subset of cancer cells influences their relative sensitivity to ATM and/or ATR inhibitors." (PMID 19903334, 2009). "At a molecular level, ATM is thought to contribute to cancer protection through two main mechanisms." (PMID 19421407, 2009). "Observations on cancer cell proliferation and survival based on the use of ATM/ATR inhibitors should thus be interpreted with caution." (PMID 19903334, 2009). "Addition of these agents to cancer cells previously rendered senescent by exposure to genotoxins suppressed the ATM mediated p21 expression required for the survival of these cells." (PMID 19903334, 2009). "EP300, ISGF3G, STAT1, and STAT3 are up regulated in 8/13 of cancer models, while ATM, BAX, BCL2L11, HTATIP2, LGALS3, MAPK1, and TP73L are down regulated in half of cancer models." (PMID 19402918, 2009). "The ataxia telangiectasia mutated (ATM) and the ATM- related (ATR) kinases play a central role in facilitating the resistance of cancer cells to genotoxic treatment regimens." (PMID 19903334, 2009). "It has been recently reported that ATM prevents cancer progression through detection and response to oncogene-induced DNA replication stress and DNA damage." (PMID 21892312, 2008). "Clearly, more studies are needed to establish the role of ATM-dependent mitochondrial biogenesis in dietary modulation of cancer and aging." (PMID 18431490, 2008). "The tumorigenic events early in the progression of major human cancer types activate the ATR/ATM-regulated checkpoint as a guard against tumor progression and genetic instability." (PMID 17907806, 2007).
cancer (continued). "The establishment of ATM heterozygosity is essential for the estimation of cancer risks and genetic counselling." (PMID 14970866, 2004). "It has been postulated and supported by limited experimental evidence that the presence of ATM missense mutations, in contrast to ATM truncating mutations, may result in a different cellular phenotype after exposure to IR and alter the risk of developing cancers in heterozygote carriers." (PMID 14970866, 2004). "Specifically, we observed ATM/ATR-dependent increase in expression of PD-L1 on the cancer cells." (PMID 42094069, 2026). "Thus, ATM inhibitors are actively studied to impair cancer cell DNA repair, disrupt cell cycle checkpoints, and enhance sensitivity to radiotherapy or chemotherapy." (PMID 41190241, 2025). "Although previous studies in mice have indicated that concurrent deficiencies in POLΘ and ATM can be partially synthetic lethal, our data suggest that cyclin D1 overexpression may be a useful biomarker for combined POLΘ and ATM inhibition in cancer treatment." (PMID 40608419, 2025). "For instance, the overexpression of ATM, DNA-PKcs, or RAD 51 (master regulators of HR and NHEJ) is associated with radioresistance in cancer cells, and the use of their inhibitors could restore the efficacy of RT." (PMID 40650150, 2025). "ATM was the only HR-DDR gene that contributed to other cancers." (PMID 40065011, 2025). "This vulnerability is being investigated in multiple cancer types through the development of ATM inhibitors and specifically in PDAC patients with germline BRCA1/2 mutations using the PARP inhibitor Olaparib, which provides some optimism for future patient outcomes." (PMID 40723241, 2025). "In the next section we describe the main ATR, ATM, Chk1 and Chk2 inhibitors used in preclinical experiments and/or clinical trials and explain how these drugs, alone or in combination, may help in cancer treatment." (PMID 40422251, 2025). "These mutations in ATM and TP53BP1 could lead to the partial loss of DNA damage repair function observed in many human cancers, although further studies are required to confirm." (PMID 40340757, 2025). "Several ATM/ATR inhibitors have been reported to sensitize cancer cells to IR." (PMID 40332379, 2025). "Unlike ATR, which is essential in numerous organisms and whose mutations can lead to embryonic lethality, ATM is not essential for viability and is often mutated, contributing to cancer development." (PMID 39968096, 2025). "While the precise mechanisms by which aberrations in ATM, ATR, and DNA-PK contribute to diverse phenotypic outcomes remain unclear, alterations in these genes are strongly linked with specific cancer subtypes." (PMID 40256842, 2025). "Patients with tumors exhibiting high ATM activity may particularly benefit from pharmacologic ATM inhibition to sensitize cancer cells to RT-induced DNA damage." (PMID 40883442, 2025). "These patented compounds collectively highlight a growing trend in ATR, ATM and DNA-PK targeted cancer therapies, with increasing emphasis on combination approaches, improved drug delivery methods, and multi-targeted kinase inhibition to enhance treatment efficacy and overcome resistance mechanisms." (PMID 40256842, 2025). "ATM also exerts a significant influence on glucose metabolism in oncogene-driven cancers." (PMID 40256842, 2025). "We suggest that additional factors—such as family history, the age at which cancer was diagnosed in relatives, and other hormonal risk factors—can be taken into account when evaluating the appropriateness of RRBSO in ATM variant carriers within a shared decision-making process." (PMID 39984762, 2025). "Additionally, gallic acid promotes G1 and G2/M cell cycle arrest via ATM-Chk2 activation, halting proliferation of damaged cancer cells." (PMID 41226270, 2025).
cancer (continued). "In individuals with A-T, the ATM protein is either absent or not functional, which can lead to an accumulation of DNA damage and an increased risk of developing cancer." (PMID 39996890, 2025). "Finally, Tpm3.1/3.2 has been suggested as a target for cancer therapy, and we showed that ATM-3507 effectively inhibits the growth and motility of DLBCL cells." (PMID 41268543, 2025). "The PGV rate was largely contributed to by BRCA2 (1.7%), ATM (1.3%), CHEK2 (1.1%) and BRCA1 (0.5%) and PGVs in these genes were found at significantly higher rates in the high risk localized and advanced PCa cohort compared to cancer-free males." (PMID 40832411, 2025). "IFI16 interferes with ATM activity, which is required for cancer cell fitness; thus, it stands to reason that IFI16 may additionally be lactylated during cancers." (PMID 39772686, 2025). "Noteworthy to mention that the drug discovery endeavours employed robust drug design strategies and culminated into a plethora of tractable ATM/ATR/DNA-PK inhibitors that on exhaustive explorations might emerge as cancer therapeutics in the long run." (PMID 40256842, 2025). "During the study period, moderate cancer risk genes such as ATM, CHEK2, and BARD1 were not analyzed in Denmark." (PMID 40408052, 2025). "Targeting ATM could have beneficial effects on DNA repair with positive effects in cancer patients and neurodegenerative disorders, but could also disrupt the balance between activation and repression of genes." (PMID 40231485, 2025). "Importantly, several key ferroptosis drivers and suppressors, including MAPK1, TLR4, ATM, ULK2, NFS1, and HMOX1, have been identified, offering potential therapeutic targets to modulate cancer cell susceptibility to ferroptosis." (PMID 40868287, 2025). "However, although there is an association of ATM protein loss in PDAC with shorter patient survival, a robust expression of ATM protein is retained in cancer cells in the vast majority (>80%) of PDAC cases." (PMID 40723241, 2025). "The utility of ATM-3507 as a potential cancer therapy depends on the balance between its efficacy and toxicity, which could be due to off-target effects." (PMID 41268543, 2025). "However, ATM-regulated angiogenesis is understood to be only in pathological conditions such as cancer." (PMID 38933336, 2024). "It is, however, defined as ‘benign’ in ClinVar (VCV000003048) and although ATM SNPs are associated with both cancer types in GWAS studies, this variant has not reached significance." (PMID 38338943, 2024). "Background/Objectives: BRCA1, BRCA2, ATM, and CHEK2 are known cancer predisposition genes (CPGs), but tumor risk in patients with simultaneous pathogenic variants (PVs) in CPGs remains largely unknown." (PMID 38929805, 2024).
cancer (continued). "The ATM gene plays different roles in cellular processes like energy production, oxidative homeostasis, telomere maintenance, chromatin remodeling, and genomic integrity, which are considered crucial processes in the context of cancer progression." (PMID 38784039, 2024). "For instance, mutations in genes such as SNCA (α-synuclein), ATM (ataxia telangiectasia mutated), PARK2 (parkin), PARK8 (LRRK2), MC1R (Melanocortin 1 receptor) and PTEN (Phosphatase and tensin homolog) have been identified in both PD and certain cancers." (PMID 39563740, 2024). "Interestingly, we found that acid-exposed cancer cells exhibited a preferred response to inhibitors of ATM and ATR (vs. corresponding cells at physiological pHe)." (PMID 38366255, 2024). "Common mutations in DDR-associated genes, such as BRCA2 and ATM, in CDX2-suppressed cancers may offer additional therapeutic opportunities for treatment with PARP inhibitors or inhibitors of ATM that are in development." (PMID 39452477, 2024). "ATM, BRCA2, and BRCA1 mutations have been well characterized in breast, ovarian, and other cancers." (PMID 39132489, 2024). "CHEK2 rMSVs are also associated with smaller risks of a similar range of cancers; for ATM (but not CHEK2), the risks appear to be restricted to a small subset of rMSVs." (PMID 39209703, 2024). "Some studies have shown that cancer patients with ATM mutations have benefited from ICB therapy compared to those without ATM mutations, as ATM mutations were found to be correlated with TMB-H, increased expression of PD-L1 and ISGs." (PMID 39033176, 2024). "Within cancer cells, spontaneously sublethal activation of apoptotic caspases and nucleases, resulting in constitutive DNA double-strand breaks and subsequent persistent activation of DNA damage response kinase ATM." (PMID 38977663, 2024). "These treatments were offered based on comprehensive genomic profiling, which identified POLE and ATM mutations associated with many malignant tumors, a finding that has not been previously reported." (PMID 38933440, 2024). "Pathogenic variants of ATM (ataxia-telangiectasia mutated), CHEK2 (checkpoint kinase 2), PALB2 (partner and localizer of BRCA2), and XRCC2 (X-ray repair cross-complementing 2) tumor suppressor genes (TSGs) have been associated with the development of cancers." (PMID 38784039, 2024). "Furthermore, the mutation frequencies of DNA damage repair genes ATM and metabolism-associated genes GGT1 were significantly higher in cancer tissues than benign nodules." (PMID 38886866, 2024). "Indeed, KU-10069, an ATM inhibitor, was previously screened as a senolytic candidate and reported to induce cancer cell apoptosis." (PMID 38816370, 2024). "In agreement with previous studies in different cancer models that combined ATM or PARP inhibitors with either proton or carbon ion irradiation, we determined that pharmacological inhibition of these pathways attenuated cell survival in combination with high LET 223Ra radiation." (PMID 38672592, 2024). "Despite this reciprocal interaction, while ATM germline mutations are well-established as a genetic modifier in LFS and other cancer predisposition syndromes, much less is known about the role of its cofactor ATMIN in human cancer." (PMID 39439949, 2024). "By elucidating ATM’s broader regulatory network in DNA repair processes, these analyses could uncover novel therapeutic targets and pathways for cancer treatment." (PMID 38807759, 2024).
cancer (continued). "In addition, recent studies have demonstrated that activation of ATM/ATR/Chk1 kinase in response to DNA double-strand breaks by irradiation can enhance PD-L1 expression in cancer cells." (PMID 39001550, 2024). "The risks of other cancers are also elevated in BRCA1-, BRCA2-, and ATM-variant carriers." (PMID 38929805, 2024). "Besides metabolic rewiring, we identify an increase in tetraploid cell frequency and DNA damage response as consistent hallmarks of acid-exposed cancer cells, supported by the activation of ATM and ATR signaling pathways." (PMID 38366255, 2024). "Besides, accumulating evidence has shown that ATM activation is involved in cancer cell resistance to chemotherapy." (PMID 36650267, 2023). "Briefly, in quiescent normal and cancer cells, ATM homodimers are present in the cytoplasm." (PMID 36900274, 2023). "Using preclinical mechanistic approaches and clinical datasets, we establish functional ATM deficiency as a principal DNA repair defect in ES and the compensatory ATR signaling axis as a collateral dependency and therapeutic target in FET rearranged cancers." (PMID 37398210, 2023). "As the MRN complex plays a crucial role in ATR and ATM activation in response to RS and DSBs, respectively, MRN complex inactivation may disturb the ATR/ATM-dependent anti-cancer barrier, leading to cancer progression." (PMID 37509263, 2023). "Multiple cytokines/chemokines were detected in the culture media, suggesting that ATM inhibition could substantially augment IR-induced inflammatory signaling in cancer cells." (PMID 36656721, 2023). "ATM is also thought to be involved in cancer progression, metastasis, and chemoresistance." (PMID 36765693, 2023). "Cancer susceptibility in patients with ATM and RAD51B alterations are still evolving with recent studies implicating these genes in a number of cancers; however, their contribution to CRC carcinogenesis at this time is unknown." (PMID 36611031, 2023). "For example, loss of ATM in tumors makes tumors more rely on ATR-mediated intra-S and G2/M checkpoints, and inhibition of ATR could selectively kill cancer cells with ATM deficiency." (PMID 38041093, 2023). "However, certain tumor cells in the advanced stages exhibit enhanced ATM signaling, which benefits cancer cell survival, resistance to radiation and chemotherapy, biosynthesis, proliferation, and metastasis." (PMID 37081847, 2023). "In addition to Olaparib, the ATM inhibitor (ATMi) can also induce the interferon response and sensitize cancer cells to ICB in preclinical models." (PMID 37174688, 2023). "The direct testing of ATM-deficient PCa models have demonstrated sensitivity to ATR inhibitors that was further potentiated by the addition of PARP inhibitor, a combinatorial effect that has been observed in several cancer types." (PMID 38201511, 2023). "Alterations of BRCA1/2 and ATM may lead to homologous recombination deficiency (HRD), increasing the risk of breast‐, ovarian‐, prostate‐, and other cancers." (PMID 36653904, 2023). "Retardation in radiation-induced ATM nucleo-shuttling (RIANS) involving the delay of recognition of DSBs and their repair indicate a default in coping with DSBs related to either radiation sensitivity (tissue sensitivity) or radiation susceptibility (cancer)." (PMID 37511215, 2023). "Furthermore, to benefit cancer cells, oxidised ATM in CAF phosphorylates the Serine490 amino acid of GLUT-1 and thus promotes its translocation to the plasma membrane." (PMID 36761981, 2023). "When homologous recombination repair genes BRCA1/2, ATM, PALB2, and CHEK2 are inactive, a variety of error-prone and non-conservative DNA repair pathways are used, increasing the incidence of cancer and worsening its prognosis while also causing genomic instability." (PMID 37732318, 2023).